DHRS11 (dehydrogenase/reductase 11)
Description:
Catalyzes the conversion of the 17-keto group of estrone, 4- and 5-androstenes and 5-alpha-androstanes into their 17-beta-hydroxyl metabolites and the conversion of the 3-keto group of 3-, 3,17- and 3,20-diketosteroids into their 3beta-hydroxyl metabolites. Exhibits reductive 3-beta-hydroxysteroid dehydrogenase activity toward 5-beta-androstanes, 5-beta-pregnanes, 4-pregnenes and bile acids. May contribute to the metabolism of adrenal-derived androgen precursors. Reduces 11-keto-4-androstene-3,17-dione (11KA4) and 11-keto-5alpha-androstane-3,17-dione (11K-Adione) into potent androgens 11-ketotestosterone (11KT) and 11-ketodihydrotestosterone (11KDHT), respectively. May also reduce endogenous and exogenous alpha-dicarbonyl compounds and xenobiotic alicyclic ketones.
Synonyms: SDR24C1; MGC4172; ARPG836; spDHRS11
Tractability: Small molecule: a structure with a bound ligand is known; it has a high-quality binding pocket. Antibody: UniProt places it where antibodies can reach, with high confidence; UniProt predicts a signal peptide or a membrane-spanning region; its Gene Ontology location is reachable by antibodies, with medium confidence.
Gene: Protein-coding gene on chromosome 17 (36,591,797 to 36,600,805, forward strand). Ensembl gene ENSG00000278535.
Subcellular location: Secreted
Subcellular location (Human Protein Atlas): Cytosol; Golgi apparatus; Predicted to be secreted
Gene Ontology:
Molecular function: 17-beta-hydroxysteroid dehydrogenase (NADP+) activity; 3-beta-hydroxysteroid 3-dehydrogenase (NADP+) activity; estradiol 17-beta-dehydrogenase [NAD(P)+] activity; oxidoreductase activity, acting on the CH-OH group of donors, NAD or NADP as acceptor
Biological process: steroid biosynthetic process; estrogen biosynthetic process
Cellular component: extracellular region
Genetic constraint (gnomAD): Loss-of-function variants: 18 observed, 29.42 expected, observed/expected ratio (o/e) 0.61, 90% interval 0.42 to 0.91. The upper end of that interval is the gene's LOEUF score, 0.91, which puts it in group 3 of 6, group 1 being the genes least tolerant of losing a copy. Missense variants: 300 observed, 323.71 expected, observed/expected ratio (o/e) 0.93, 90% interval 0.84 to 1.02. Synonymous variants: 123 observed, 128.62 expected, observed/expected ratio (o/e) 0.96, 90% interval 0.82 to 1.11.
Homologues: Orthologues: chimpanzee DHRS11 (99% identical), dog DHRS11 (93% identical), guinea pig DHRS11 (93% identical), mouse Dhrs11 (93% identical), rat Dhrs11 (92% identical), rabbit DHRS11 (92% identical), pig DHRS11 (89% identical), zebrafish dhrs11a (73% identical), tropical clawed frog dhrs11 (66% identical), Drosophila melanogaster CG9150 (41% identical), Drosophila melanogaster CG40486 (40% identical), Drosophila melanogaster CG9360 (39% identical), and 12 more. Paralogues in human: DHRS2 (23% identical), DHRS7 (23% identical), DHRS7B (23% identical), RDH8 (22% identical), DHRS4 (22% identical), HSD11B1L (22% identical), CBR3 (21% identical), HSD11B1 (20% identical), CBR1 (20% identical), DHRS7C (19% identical), HSDL2 (18% identical), DHRS4L2 (17% identical), and 1 more.
Diseases named in the same sentence as DHRS11 in open-access papers:
DHRS11 is named in the same sentence as 14 diseases in open-access papers, as found by Europe PMC text mining. Sharing a sentence is not in itself a finding about the gene and the disease. The quoted sentences say what the papers report.
Huntington disease (1 paper, 2024). Huntington disease (HD) is a rare neurodegenerative disorder of the central nervous system characterized by unwanted choreatic movements, behavioral and psychiatric disturbances and dementia. "Similarly, in cattle, targeted genes like ATG2B and DHRS11 of fs-cb-miRs participate in the pathways of Huntington disease and steroid biosynthesis, respectively." (PMID 38674383, 2024).
Insulin resistance (1 paper, 2019). Increased resistance towards insulin, that is, diminished effectiveness of insulin in reducing blood glucose levels. "Dehydrogenase/reductase member 11 (DHRS11) and AKR1B15 are novel biomarkers for the development of insulin resistance." (PMID 30678306, 2019).
rectal cancer (1 paper, 2025). A primary or metastatic malignant neoplasm that affects the rectum. "This study identified a TRP channel-related gene signature (BMP5, DHRS11, GLTP, NFE2L3, and TMCC3) that predicts rectal cancer prognosis and modulates tumor–immune crosstalk." (PMID 40963625, 2025). "Through qRT-PCR experiments, we found that DHRS11, GLTP, and NFE2L3 have dysregulated expression in rectal cancer tissues." (PMID 40963625, 2025).
DHRS11 also shares sentences with these, for which no sentence is quoted: tumor (3 papers); cancer (2); breast carcinoma (1); Chagas disease (1); colorectal cancer (1); Hepatitis C (1); hereditary angioneurotic edema (1); hyperprolinemia type 2 (1); mastitis (1); prostate carcinoma (1); schizophrenia (1).